TNF (tumor necrosis factor)
Diseases named in the same sentence as TNF in open-access papers (continued):
Sharing a sentence is not in itself a finding about the gene and the disease.
hepatocellular carcinoma (continued). "By using computational modeling, we first showed that TNF-induced activation and downstream signaling is qualitatively comparable between primary mouse hepatocytes and immortalized hepatocellular carcinoma (HCC) cells." (PMID 28878689, 2017). "Our results also validate recent results observed in a hepatoma cell lines resistant to Sorafenib, where it was proposed that resistance to the drug treatment was associated with high CD47 protein levels achieved by the binding of NFKB2 subunit to the CD47 promoter upon TNF-α stimulation." (PMID 28378740, 2017). "Another example of hypoxia and inflammation crosstalk in cancer is observed in Hepatocellular Carcinoma (HCC), where TNF-α is one of the cytokines constantly activated by NF-κB, through the Tumour Associated Macrophages (TAMs)." (PMID 28536364, 2017). "A study on patients with pancreatic cancer showed that serum TNF-α levels were inversely correlated with BMI, hematocrit, hemoglobin, serum protein and albumin levels and similar observations were made in patients with prostate cancer and hepatocellular carcinoma." (PMID 26856534, 2016). "Hepatocellular carcinoma (HCC) is the third most common cause of cancer-related death worldwide and represents a paradigm of inflammation-induced cancer, indicating a strong link between activation of pro-inflammatory pathways such as TNF-induced NFκB signaling and tumorigenesis." (PMID 23293603, 2012). "Moreover, addition of TNF or IL-1 to Hep3B hepatoma cell cultures decreases apoM mRNA levels." (PMID 22512779, 2012). "Similarly, autophagy protects hepatoma cells from TNF-induced cytotoxicity by blocking caspase-8 activation and the mitochondrial death pathway, while its inhibition elevates TNF levels and caspase-8 activity, suggesting therapeutic potential in TNF-mediated tissue damage." (PMID 41254398, 2025). "In hepatocellular carcinoma (HCC), LPS promotes cell survival, proliferation, invasion, and production of pro-inflammatory mediators, including TNF-α, iNOS, IL-1β, IL-6, CCL-2, CCL-22, vimentin, and epidermal growth factor receptor (EGFR), through the induction of TLR4 signaling." (PMID 40444051, 2025). "PKD2 expression was found to be upregulated in hepatocellular carcinoma (HCC) and shown to enhance TNF-induced EMT and invasion of HCC cells." (PMID 39408603, 2024). "In a recent study, hepatocellular carcinoma (HCC) cells secreted exosomal circUHRF1 to suppress NK cell-derived IFN-γ and TNF-α levels by upregulating TIM-3 expression, presenting a novel mechanism for tumor resistance." (PMID 39415291, 2024). "In hepatoma cells and primary hepatocytes, ADAM10 and its closest relative ADAM17 (also recognized as tumor necrosis factor α (TNFα) converting enzyme or TACE) show the highest expression levels." (PMID 37967063, 2023). "TNF-α and IFN-γ have been shown to synergistically induce cell death in different cell types such as murine hepatoma cells, a myeloblastic leukemia cell line and oligodendroglioma cells." (PMID 37610672, 2023). "Similarly, a clinical observational study also reported decreased levels of circulating TNF-α and IL-6 in hepatocellular carcinoma (HCC) patients after Lenvatinib treatment." (PMID 36839733, 2023). "S100A8/S100A9 co-expression in hepatocellular carcinoma cells promotes malignant progression by induction of ROS, down-regulation of p38 MAPK signaling, cell survival, and resistance to tumor necrosis factor (TNF)-α-induced apoptosis." (PMID 36609243, 2023). "A role for TNF-α in promotion of EMT was shown in CCA and hepatoma cell lines by increasing the expression of Snail and reducing E-Cadherin, and stabilizing ß-Catenin." (PMID 36845555, 2023). "The genes in clusters 5 and 12 were enriched in functions related to the following KEGG pathways: cell cycle, NF‐κB, hepatocellular carcinoma, MAPK, pathways in cancer, VEGF, Rap1, TNF, TGF‐β, Wnt, AMPK, mTOR, PI3K‐Akt, HIF, and Hippo signaling." (PMID 37085918, 2023).
hepatocellular carcinoma (continued). "In hepatocellular carcinoma (HCC), CD66b + TANs exhibited increased expression of TNF-α, IL-8, CCL2 and cell-death ligand 1 (PDL1) and decreased CD62L expression." (PMID 37212866, 2023). "This study reports that TNF-α induces release of sLDL-R and such form of the receptor can bind to the LDL-C inhibiting its clearance by human hepatoma cells in vitro." (PMID 37861809, 2023). "Cytokines produced by these resident as well as infiltrating macrophages such as TNFα, transforming growth factor β (TGF-β), interleukin 6 (IL-6) and 18 (IL-18) are highly associated with the development and progression of hepatocellular carcinoma (HCC)." (PMID 36276076, 2022). "In hepatoma cell lines Hep3B and PLC/PRF/5, TNF-induced EMT increased the expression of PD-L1, PD-L2, CD73, and B7-H3, while reversing EMT reduced the expression of PD-L1, PD-L2, CD73, and B7-H3." (PMID 35897925, 2022). "For patients with hepatocellular carcinoma, the coexpression of CD161 and IL-7R enhances IL-2, TNF-α, and perforin expression which improve prognosis." (PMID 35028320, 2022). "Ginsenoside Rb1 inhibited TNF-α-induced MMP-9 production in both H9c2 and liver carcinoma HepG-2 cells." (PMID 36432152, 2022). "After removal of ZOL, hepatoma cell lines were again co-cultured with IHL and were then able to trigger a significant increase in Vγ9Vδ2 T-cell effector function (IFN-γ, TNF-α, IL-2 expression)." (PMID 35296658, 2022). "M2 TNF-α secretion has been shown to promote EMT and induce “stemness” in an in vitro hepatocellular carcinoma model." (PMID 33986746, 2021). "TNF-α and IFN-γ induced IL-32 in primary human hepatocytes and hepatoma cells that regulate the transcription of HBV core promoter by downregulating HNF1-α and HNF4-α." (PMID 33868257, 2021). "TNF- α released by M2 macrophages can promote the epithelial-mesenchymal transformation and cancer stemness of HCC, indirectly promote the dedifferentiation of hepatocellular carcinoma cells and promote the progress of HCC." (PMID 35096588, 2021). "In hepatocellular carcinoma cells, CTSC accelerates proliferation and metastasis by activating the TNF-α/p38 pathway." (PMID 34326696, 2021). "We also showed that the enhanced intralysosomal accumulation of MT abrogates the TNF-mediated LMP, eventually protecting hepatoma cells against the lethal action of the cytokine." (PMID 33809171, 2021). "The low level accumulation and infiltration of NK cells and less secretion of TNF-α and IFN-γ were discovered in 294 cases with untreated and advanced hepatocellular carcinoma." (PMID 32075046, 2020). "M2 TAMs secrete TNF-α, activate the Wnt/β-catenin pathway in SMMC-7721 hepatoma cells, and induce the appearance of EMT and CSCs." (PMID 32210805, 2020). "The hepatoma cell line Hepa-1c1c7 (ATCC® CRL-2026TM) exposed to palmitate presented increased JNK phosphorylation, IL-6 and TNF-α mRNA compared to cells exposed to vehicle solvent alone." (PMID 31913329, 2020). "IL-6 can promote hepatocellular carcinoma (HCC) growth and metastasis via antagonism of TNF-α and IL-1β immune response." (PMID 31867004, 2019). "Besides, TIPE2 suppressed TNF-α-mediated metastasis of hepatocellular carcinoma (HCC) cells by inhibiting nuclear factor kappa B (NF-κB) and Erk1/2, indicating TIPE2 as a plausible target against HCC metastasis." (PMID 31817720, 2019). "When presented to CD8+ T or CD4+ T lymphocytes, the epitopes activated specific CTLs to secret high levels of TNF-α and IFN-γ and stimulated specific immune response against hepatocellular carcinoma." (PMID 29805966, 2018). "It has been further demonstrated that TNFα provokes the processing of SREBP-1c in ethanol-exposed hepatoma cell lines, resulting in the inappropriate induction of lipogenic enzymes, thus suggesting that adiponectin may counteract hepatic lipid accumulation through the antagonism of TNFα." (PMID 29735928, 2018).
hepatocellular carcinoma (continued). "In this study the evaluation of the cytokinome profile of human hepatoma HepG2 cells evidenced a modulation of vascular endothelial growth factor (VEGF) and tumor necrosis factor (TNF)-α after PECS treatment." (PMID 27775667, 2016). "Irradiation significantly upregulated the mRNA expressions of FasL, TRAIL, TNF-α, and TGF-β1 in hepatoma cells, and downregulated the mRNA expressions of IGF-1 and PDGFB, but no obvious effects on the expressions of VEGFA, PDGFA, and IL-6." (PMID 27431384, 2016). "At 50 μM, RES inhibits TNF-α-mediated MMP-9 expression and invasion of human hepatocellular carcinoma cells." (PMID 26043036, 2015). "Here, we have approached this question by performing ChIP-chip assays on human hepatoma HepG2 cells and analyzing SND1 binding modulation by proinflammatory TNFα." (PMID 26323317, 2015). "Furthermore, TNFα and IL1β treatment of Hep3B human hepatoma cells and mice resulted in decreased expression of RXRα, PPARα, PPARγ, LXRα, as well as their co-activators PGC1α and PGC-1β, which may contribute to the cytokine induced modulations in hepatic energy homeostasis." (PMID 24112857, 2013). "HCV core protein has been reported to induce overexpression of tumor necrosis factor-α (TNF-α) in the liver of transgenic mice and human hepatoma cell lines." (PMID 22451839, 2012). "VEGF, TGF beta, TNF alpha, PDGF and AGT are all intimately related to the progression of fibrosis to cirrhosis and hepatocellular carcinoma in mammals." (PMID 21901081, 2011). "Functional analysis demonstrates that the HCV TCR-transduced both CD4+ and CD8+ T cells produce interferon-γ, TNF-α, and to a lesser extent, IL-2 when stimulated with the peptide-loaded targets or HCV+ hepatoma cells." (PMID 20686664, 2010). "IFN-α/β, gamma interferon (IFN-γ) and tumor necrosis factor alpha (TNF-α) suppress HBV replication in immortalized murine hepatocytes and human hepatoma cells by preventing the formation of viral capsids or disrupting capsid integrity." (PMID 19374779, 2009). "In a hepatocellular carcinoma case study, all 5 EpiMII-designed epitopes could markedly activate CD4+ T cells in vitro and induce the secretion of interferon-γ and tumor necrosis factor-α." (PMID 42306778, 2026). "It has been shown that TNF-α upregulation in mouse hepatocytes triggers NF-kB accumulation and TNF-α inhibition, resulting in the apoptosis of transformed hepatocytes and their progress to hepatocellular carcinoma." (PMID 40723879, 2025). "The KEGG enrichment analysis indicated that these genes may be involved in several signaling pathways, including PI3K-Akt, MAPK, TNF, T cell receptor, IL-17, PD1/PDL1, apoptosis, and pathways related to colorectal and hepatocellular cancers." (PMID 40732339, 2025). "We investigated whether the induction of TRIM21 occurs in response to TNF-α and IFN-γ in human hepatoma cell lines and PHHs." (PMID 38780244, 2024). "Based on the numbers and corrected p-values of these DEGs, which were adjusted by the Bonferroni correction, the DEGs in PD-treated HepG2 cells were significantly enriched in the hepatocellular carcinoma (HCC) set, TNF signaling pathway, Hippo signaling pathway, steroid biosynthesis pathway, etc.." (PMID 36672157, 2023). "In hepatocellular carcinoma, on the one hand, TNF-α can activate cathepsin C, and, on the other hand, cathepsin C can also activate the TNF-α/p38MAPK pathway, which has a close relationship with the growth of hepatocellular carcinoma." (PMID 37398678, 2023). "A time-course study indicated that TNF-α acts as a priming factor to increase HDGF release from hepatoma cells during H. p. infection, and HDGF is also known as an intermediator that amplifies and maintains downstream COX-2/TNF-α signaling through the activation of nuclear factor kappa B (NF-κB)." (PMID 35053302, 2022).
hepatocellular carcinoma (continued). "ZOL pre-treatment of the hepatoma cell lines was again required in order to evoke substantial IFN-γ and TNF-α expression by the expanded blood Vγ9Vδ2 TRM, which was reduced in a dose-dependent manner by the addition of Mevastatin, confirming the dependence on tumour cell IPP expression." (PMID 35296658, 2022). "Additionally, CARD oil decreased the levels of TNF-α, IL-1β and NF-κB in the DENA-induced hepatocellular carcinoma." (PMID 36354677, 2022). "Anti-cancer effects of sPD-1-CH50 included intensification of macrophages and cytotoxic T lymphocytes’ (CTLs) cytotoxic activity through inducible nitric oxide synthase (iNOS), tumor necrosis factor-alpha (TNF-α), IFN-α with demonstration of in vivo restriction of hepatoma growth and invasiveness." (PMID 34531847, 2021). "Consistently, the overexpression of GCL was found to inhibit TNF-α-induced activation of NF-κB, AP-1, and JNK in rat hepatoma cells, while increase in GSH synthesis was shown to down-regulate the NF-κB activation and TNF-α release in LPS-stimulated alveolar type II (AT-II) epithelial cells." (PMID 33238435, 2020). "This difference could be explained by the much more pronounced cytotoxic effect of TNF in human cancer cells in comparison to AZT, which we also observed in hepatoma cells." (PMID 32316635, 2020). "Human hepatoma Huh-7 cells transfected with an NS5A vector have demonstrated an elevation of ROS with resulting activation of NF-KB and STAT-3 pathways that then led to the release of various array of cytokines, including IL-6, IL-8, TNFα, and TGFβ." (PMID 31540136, 2019). "Notwithstanding, CPT1A mRNA was induced in expression (panel A1-A3) in PHHs and hepatoma cell lines after lipid but not the combined lipid and TNFα treatment." (PMID 30547786, 2018). "Furthermore, in good agreement with these in vivo results, transduction of Hepa1-6 hepatoma cells with SHARPIN, HOIL-1L, or HOIP shRNA adenovirus induced apoptosis of these cells in response to tumor necrosis factor-α (TNFα) stimulation." (PMID 28165393, 2017). "The Morris-7777 hepatoma tumor model is characterized by anorexia and the absence of pro-inflammatory cytokines such as interleukin-6 (IL-6) or tumor necrosis factor-α (TNF-α) but elevated macrophage-inhibitory cytokine-1 (MIC-1)." (PMID 28475119, 2017). "Data indicate that NF-κB activation by IL-1β/TNFα, likely mediated by an active proximal NF-κB site at −85 to −76 bp relative to the TSS, supports STAT1 binding to the iNOS promoter in murine Hepa1-6 hepatoma cells." (PMID 28824623, 2017). "To determine whether inflammatory stimuli such as TNF-α and LPS can interfere with type 1 IFN signaling, we sought to determine whether pretreatment of hepatoma cells with TNF-α or LPS blocked IFN-α signaling." (PMID 27009955, 2016). "Unlike in MCD, multiple cytokines such as IL-6, TNF-α and IL-1 are involved in the pathogenesis of RA-anemia, and we therefore analyzed the effects of cytokine combinations on hepcidin production in hepatoma cells." (PMID 24286116, 2013). "Overexpression of regucalcin rescues cell death and apoptosis induced with various factors (including TNF-α, TGF-β, LPS, insulin, IGF-I, Bay K 8644, PD98059, dibucaine, thapsigargin, or sulphoraphan), which those signaling mechanisms are different in the hepatoma cells and normal kidney cells." (PMID 23670020, 2013). "In addition to IFNs, TNF-α also inhibits both HBV Enh II/Cp and CMV IE promoter activities in hepatoma cells." (PMID 23936368, 2013). "New treatment strategies are needed, including new chemotherapeutic agents like tumor necrosis factor (TNF)-related apoptosis in esophageal, colon, pancreas, and liver carcinomas in vitro and in vivo, which was also analyzed and suggested to be an inducer of apoptosis in human fibrosarcomas." (PMID 23015777, 2012). "We also observed that SMT and NAC did not reverse the inhibitory effect of TNF-α on PbA-infected HepG2-CD81 hepatoma cells (data not shown)." (PMID 21394207, 2011).
hepatocellular carcinoma (continued). "Expression of FOS was enhanced in human omental microvascular endothelial cells when incubated with TNF-α for 10 min, whereas BCL3, a nuclear protein primarily found in B lymphocytes, increased when human hepatocellular carcinoma cell lines (HepG2) were stimulated with TNF-α." (PMID 19925655, 2009). "Interestingly, levels of TNF-α are increased in cachectic cancer patients and are elevated in severe combined immunodeficient (SCID) mice implanted with Morris hepatoma MH7777 cells." (PMID 17678552, 2007). "Thirdly, we used the rat hepatoma cell line McA RH 7777 for transient expression experiments, which also did not indicate any change in sensitivity to TNF upon cathepsin overexpression." (PMID 14562034, 2003). "In addition, FasL surface expression was not detectable on co-cultured NK cells and tumor necrosis factor-α secretion by NK cells was not increased upon co-culture with HDV-infected hepatoma cells (data not shown)." (PMID 38143742, 2023). "In the liver, TNF mediates hepatocellular death and seems to be involved in sterile inflammation, viral hepatitis, AIH, and hepatocellular carcinoma (HCC)." (PMID 35122118, 2022). "The IGF-axis is also modulated by miR-615-5p in NK cells of hepatocellular carcinoma (HCC) patients, in which upregulation of miR-615-5p directly represses IGFR1 signaling and reduces the cytotoxic markers NKG2D, TNF-a and perforins." (PMID 32605009, 2020). "Mechanically, hepatocellular carcinoma (HCC) can secreted circUHRF1 in an exosomal manner, inhibiting the secretion of NK cell-derived IFN-γ and TNF-α and inhibiting NK cell function by up-regulating the expression of TIM-3 through degradation of miR-449c-5p." (PMID 33613544, 2020). "In human hepatocellular carcinoma (HCC), TIM-1+ Breg cells significantly suppressed the survival and TNF-α and IFN-γ production of CD8+ effector T cells." (PMID 33193391, 2020). "Interleukin 6 (IL6), tumor necrosis factor α (TNFα) and TNF receptor-1(TNFR1) have been shown to involve in oval cell proliferation and hepatocellular carcinoma (HCC) development." (PMID 27556180, 2016). "Correlation among mediators (IL-6, IL-27, TNF-α, and VEGF) with STAT proteins at diverse clinical-pathologic stages of hepatocellular carcinoma (HCC) remains limited." (PMID 25908103, 2015). "The pevonedistat+TNF-α synergistic cytotoxicity was replicated in a diverse set of other cell types, including: primary rat hepatocytes and liver Kupffer cells; the rat proximal tubule line NRK-52E; the human acute monocytic leukemia line THP-1; and the human hepatocellular carcinoma line HEP-G2." (PMID 27551465, 2015). "Neither TNF-α nor IL-6 was detected in supernatants of hepatoma 22a cells by ELISA." (PMID 21760797, 2011). "In hepatocellular carcinoma (HCC) cells, high HPSE expression was shown to induce necroptosis in adjacent microvascular endothelial cells (MVECs), thereby promoting trans-endothelial migration through the HPSE/SDC-1/TNF-α and p38 MAPK pathways." (PMID 41301515, 2025). "Consistent with this, depression of NF-κB could convert the function of TNF-α signaling from survival to death in ovarian cancer cells and promote TNF-α-induced CCA, apoptosis, and necroptosis in hepatocellular carcinoma (HCC) cells." (PMID 37375731, 2023). "In support of these findings, in a genetic model of HFD-induced NASH (nonalcoholic steatohepatitis) and HCC (hepatocellular carcinoma), treatment with ER stress alleviators PBA and TUDCA, improved disease outcomes by limiting the release of TNF by inflammatory macrophages." (PMID 32178254, 2020). "However, neither IL-6 nor TNFα could induce PD-L1 expression on hepatoma cells, with or without EZH2-silencing." (PMID 31727135, 2019).